TRAV3 (T cell receptor alpha variable 3)
Description:
V region of the variable domain of T cell receptor (TR) alpha chain that participates in the antigen recognition. Alpha-beta T cell receptors are antigen specific receptors which are essential to the immune response and are present on the cell surface of T lymphocytes. Recognize peptide-major histocompatibility (MH) (pMH) complexes that are displayed by antigen presenting cells (APC), a prerequisite for efficient T cell adaptive immunity against pathogens. Binding of alpha-beta TR to pMH complex initiates TR-CD3 clustering on the cell surface and intracellular activation of LCK that phosphorylates the ITAM motifs of CD3G, CD3D, CD3E and CD247 enabling the recruitment of ZAP70. In turn ZAP70 phosphorylates LAT, which recruits numerous signaling molecules to form the LAT signalosome. The LAT signalosome propagates signal branching to three major signaling pathways, the calcium, the mitogen-activated protein kinase (MAPK) kinase and the nuclear factor NF-kappa-B (NF-kB) pathways, leading to the mobilization of transcription factors that are critical for gene expression and essential for T cell growth and differentiation. The T cell repertoire is generated in the thymus, by V-(D)-J rearrangement. This repertoire is then shaped by intrathymic selection events to generate a peripheral T cell pool of self-MH restricted, non-autoaggressive T cells. Post-thymic interaction of alpha-beta TR with the pMH complexes shapes TR structural and functional avidity.
Synonyms: TCRAV16S1; TCRAV3S1
Gene: T-cell receptor variable (V) gene on chromosome 14 (21,723,713 to 21,724,321, forward strand). Ensembl gene ENSG00000211777.
Subcellular location: Cell membrane
Gene Ontology:
Biological process: adaptive immune response
Cellular component: immunoglobulin complex; plasma membrane
Homologues: Orthologues: macaque TRAV3 (78% identical). Paralogues in human: TRAV8-4 (59% identical), TRAV8-6 (58% identical), TRAV8-2 (57% identical), TRAV8-7 (55% identical), TRAV8-3 (54% identical), TRAV8-1 (54% identical), TRAV16 (49% identical).
Diseases named in the same sentence as TRAV3 in open-access papers:
TRAV3 is named in the same sentence as 3 diseases in open-access papers, as found by Europe PMC text mining. Sharing a sentence is not in itself a finding about the gene and the disease. The quoted sentences say what the papers report.
autoimmune disease (1 paper, 2024). A disorder resulting from loss of function or tissue destruction of an organ or multiple organs, arising from humoral or cellular immune responses of the individual to their own tissue constituents. "Genes related to these autoimmune diseases and Th17 cell differentiation, including CTLA4, IFN-ALPHA-8, IL12RB2, TRAV3, TRAV16, FOS, and VEGFA, were up-regulated in the E. coli group but down-regulated in the BL + E." (PMID 39707535, 2024).
TRAV3 also shares sentences with these, for which no sentence is quoted: COVID-19 (1 paper); tumor (1).